KRAS (KRas proto-oncogene, GTPase)
Diseases named in the same sentence as KRAS in open-access papers (continued):
Sharing a sentence is not in itself a finding about the gene and the disease.
cancer (continued). "Accordingly, BAY 11-7082 could be considered an effective inhibitor targeting NRAS, KRAS, and HRAS mutant cancer and serve as a promising candidate for more effective treatments tailored to all RAS-mutant cancers." (PMID 38982514, 2024). "In the KRAS case study, the conditions do not reflect different treatments but instead different cancer models." (PMID 38280860, 2024). "Comparison with previous studies also shows that the role of KRAS and NRAS genes in other cancers is similar and may be effective in determining molecular pathways of cancer progression." (PMID 39867023, 2024). "Notably, a previous study reported that KRAS overexpression induces numerous responsive lncRNAs including KIMAT1, which is found essential for KRAS-driven cancer cell survival and reciprocally potentiates KRAS signaling." (PMID 38104151, 2023). "The results showed that RS was closely related to KRAS signaling up, EMT and other pathways related to cancer development and metastasis, and the immune-related pathways IL6 JAK STAT3 signaling and IL2 STAT5 signaling were significantly different in patients with high and low RS." (PMID 37773804, 2023). "Together, these results suggest that the combination of SHP2 inhibition and inhibition of downstream MAPK pathways, such as cell cycle regulators, is a promising strategy for treatment of KRAS-driven cancers regardless of KRAS genotype." (PMID 36752207, 2023). "Together, the data indicate that, rather than being fixed in an active state, common KRAS mutants undergo nucleotide cycling in cancer cells (a property that is necessary for the drug to access the GDP-bound conformation)." (PMID 37258666, 2023). "These drugs, however, require a reactive cysteine residue for inhibition and cannot be used against non-G12C mutants, which constitute most KRAS alterations in cancer." (PMID 37258666, 2023). "In addition, the correlation between KRAS expression and molecular mechanisms was investigated by TIMER and Cancer Single-cell State Atlas (Cancer SEA)." (PMID 38206735, 2023). "The first one, obtained from the Cancer Imaging Archive (TCIA), consisted of 60 cases (25% EGFR, 23% KRAS); the second one, provided by the Azienda Ospedaliero-Universitaria ’Ospedali Riuniti’ of Foggia, was composed of 55 cases (16% EGFR, 28% KRAS)." (PMID 37508774, 2023). "Together, these results highlight the role of nongenetic mechanisms of drug resistance in cancer and call for closer attention to be paid to the differences in interactions of the various drug-bound ensembles of mutant KRAS." (PMID 37831779, 2023). "Here, using KRAS as a paradigm, we illustrate how this nexus between genetic and non-genetic mechanisms enables cancer cells to evade the harmful effects of drug treatment." (PMID 38002269, 2023). "In addition to MYC protein stabilization via ERK1/2 phosphorylation under normal conditions, or through ERK5 when cancer cells are treated with MEK1/2 or ERK1/2 inhibitors, our data provides a new mechanism for MYC protein regulation by KRAS oncogene." (PMID 37210549, 2023). "The molecular circadian clock is not disrupted in all cancers, and in particular seems to be maintained (albeit in an altered state) in those driven by mutated HRAS or KRAS." (PMID 37639465, 2023).
cancer (continued). "In general, KRAS mutations occur more frequently than HRAS or NRAS mutations, although this is not true for all types of cancer." (PMID 37240418, 2023). "It has recently been reported that KRAS mutant can promote Rad51 expression to increase the chemotherapy resistance of cancer cells, while inhibiting HDAC can down-regulate Rad51 to counteract Rad51-mediated resistance of cancer cells." (PMID 36793108, 2023). "The direct targeting of KRAS-mutant proteins is a powerful tool but is not the only option for treating KRAS-mutant cancers." (PMID 37190303, 2023). "Of clinical relevance, oBHV has a particular affinity for cancers with a high incidence of mutant KRAS, a negative therapeutic outcome predictor of hard-to-treat cancers such as lung, colorectal and pancreatic cancers." (PMID 36831636, 2023). "At 1L treatment start, significantly more patients with KRAS G12C–positive cancer were female, smokers, and had non-squamous histology, a higher prevalence of metastasis and programmed death-ligand 1 positivity than those with KRAS WT cancer." (PMID 37069542, 2023). "Despite KRAS has been considered a virtually undruggable target for years, several RAS signaling inhibitors have been recently developed, and many are currently being tested in clinical trials for different cancers." (PMID 36674902, 2023). "In UCEC, the same infiltration pattern was observed among samples harboring mutations of genes regulating DNA damage repair and cell cycle but not in patients with mutations of classical cancer hallmarks such as PTEN, MYC, KRAS, BAX and ect." (PMID 37917664, 2023). "Recently, BI-3406, a SOS1–KRAS interaction inhibitor, was shown to attenuate SOS1 dependent feedback reactivation induced by MEK inhibitors and thereby enhance sensitivity of KRAS-dependent cancers to MEK inhibition." (PMID 37370689, 2023). "Unlike other components of the MAPK pathway, such as KRAS, BRAF, and NRAS, MRAS has not been found to be mutated in human cancers, and perhaps this circumstance has excluded it from being an attractive anticancer target." (PMID 37996408, 2023). "In mini‐cell‐derived xenograft (CDX) models, THZ1 significantly suppressed KRAS‐G12V PDAC but not KRAS‐G12D cancer." (PMID 38037549, 2023). "We therefore used the GDC-Pan cancer database to evaluate expression profiles of GSL synthases in human cancers with (n = ~730) or without (n = ~11,038) KRAS mutation." (PMID 36709325, 2023). "We demonstrate that Z29077885 can inhibit STK33 enzymatic function in vitro and decrease cell viability regardless of the KRAS mutation status and STK33 expression level in cancer cells." (PMID 38087254, 2023). "The KRAS-G12C inhibitor development story is testimony to not take no for an answer, and pursue the targeting of cancer drivers, even if they were considered undruggable." (PMID 36688434, 2023). "We discovered that TNFA signaling through NFKB, KRAS signaling, epithelial-mesenchymal transition (EMT), the inflammatory response, hypoxia, and the interferon-gamma response, were all remarkably correlated with OMRGs in pan-cancer." (PMID 36860371, 2023). "Patients with KRAS G12C–positive cancer showed a (non-significant) numerically longer OS when treated with CIT monotherapy." (PMID 37069542, 2023).
cancer (continued). "While RTKs typically activate RAS through the GRB2-SOS1 complex without relying on SHP2, the proliferation of KRAS (G12C) mutant cancer cells in vivo necessitates SHP2 activity." (PMID 38102334, 2023). "As KRAS induces MYC, mitochondria appear to be the primary target of KRAS and MYC in cancer." (PMID 37158894, 2023). "Currently, there are no clinically approved drugs that directly thwart mutant KRAS G12D, a major driver of human cancer." (PMID 38051103, 2023). "In a lipid-deprivation context, autophagy increases to provide cancer cells with the necessary lipids in KRAS mutant tumors, but not in healthy lung tissue." (PMID 36675307, 2023). "ASOs have been explored as therapeutics for the treatment of KRAS mutant cancers; however, currently, there are no ASO therapeutics being tested in clinical trials." (PMID 38069255, 2023). "In contrast, the mRNA level of another well-known oncogene KRAS is not reduced by si78, consistent with our recent finding in other cancer cell lines being tested." (PMID 37487081, 2023). "KRAS G12V is found to be an early driver event across multiple cancer types and therefore not expected to be particularly often subclonal; however, it has been identified as a potential driver of clonal hematopoiesis." (PMID 37121998, 2023). "The small-molecule SOS1 inhibitor BI-3406 abolishes SOS1-KRAS interaction in vitro and in KRAS-dependent cancer models without affecting KRAS wild-type cells." (PMID 38023987, 2023). "AP-1-clustered sites are present only in the promoter of claudin 4, but the mRNA of this claudin is not upregulated in CMS3 or CMS1 cancers where the KRAS/MAPK pathway is mostly activated due to activating KRAS and BRAF mutations, respectively." (PMID 37998722, 2023). "Indeed, cancer cells generally display elevated replication stress due to activated drivers such as CCNE1, KRAS and MYC." (PMID 37325550, 2023). "As expected, METTL14 and KRAS Achilles scores were not correlated in cancer cell lines among these groups." (PMID 36794620, 2023). "It is noteworthy that the rs12028023 A‐allele specifically improved survival in patients with KRAS and NRAS mutant cancers, but not in those with BRAF mutant cancers, supporting a direct effect on the upstream RAS signaling pathway." (PMID 36790221, 2023). "The treatment and outcomes of KRAS-mutant cancers have not been dramatically revolutionized by direct KRAS-targeted therapies because of the lack of deep binding pockets for specific small molecule inhibitors." (PMID 37779142, 2023). "While not yet approved for mCRC, KRAS-targeted therapy has demonstrated effectiveness in other cancers." (PMID 37444625, 2023). "For instance, RAF1 and SHOC2, which encode CRAF and SHOC2 respectively, have been shown to be important in KRAS-mutant cell lines, suggesting inhibition of CRAF and SHOC2 could be used in KRAS-mutant cancer." (PMID 37669923, 2023). "Signal transducer and activator of transcription 3 (STAT3) is both a signaling molecule and a transcription factor, while the mammalian homolog of Kirsten RAS (KRAS) is a signal relaying GTP-binding protein, however, both have been popular yet elusive targets in the world of cancer therapy." (PMID 35886918, 2022). "We also examined the relationship between KRAS and DFS in cancer patients." (PMID 35563733, 2022). "The following most altered cancer genes were LRP1B (26%), PIK3CA (24%), CDKN2A (24%), PTPRD (15%), RB1 (13%), PDE4DIP (13%), PCLO (11%), KRAS (11%), FAT1 (10%), and RELN (10%), and these results partially overlap with the most altered genes depicted in the experimental cohort." (PMID 35330454, 2022).
cancer (continued). "A long line of evidence supports that homotypic two-dimensional cancer cell cultures are not optimal for the study of KRAS-dependence." (PMID 35327394, 2022). "As for the cancer cell line LS174T, two red spots were formed both for the normal allele and the G12D KRAS mutation." (PMID 35200357, 2022). "The study clearly indicates that a potentiating impact of ATO in enhancing the oxidizing effect of VC is escalated to a potent cytotoxic impact selectively in KRAS-mutant cancer cells without affecting primary and other cancer cells." (PMID 36359850, 2022). "This can be an effective combination therapy for patients with cancer that do not respond or develop resistance to KRAS G12C inhibitor treatment." (PMID 35573474, 2022). "In past decades, there were no effective therapies available for KRAS cancers and they were “undruggable” because KRAS has no hydrophobic pockets for its inhibition." (PMID 36359850, 2022). "We report here that SB-204990 treatment kills KRas-driven cancer cells in the absence of serum or deprivation of Gln." (PMID 36269753, 2022). "CTNNB1, KRAS, and NRAS are also three intersecting genes in the cancer pathway in this study, indicating that they may be key target genes regulating the development of AIS." (PMID 36399471, 2022). "These cell lines showed a spectrum of genetic dependencies on KRAS, HRAS, BRAF, CALM1-3 (the three human CaM genes), the alpha isoform of the C subunit of the PP2A enzyme (PPP2CA) and an endogenous inhibitor of PP2A in cancer, SET." (PMID 35617282, 2022). "The results showed that berberine and coptisine significantly lowered the KRAS mRNA levels in the two cancer cell lines, while not in the normal BEAS-2B cells." (PMID 36224201, 2022). "This is consistent with increased risk of KRAS-mut, and NEK tumors associated with smoking while EGFR-mut cancers are frequently observed in non-smokers." (PMID 36612014, 2022). "Several studies have demonstrated that the promoter region of many cancer-driving oncogenes, including KRAS and c-MYC, have G-rich DNA sequences that form a noncanonical, four-stranded nucleic acid structure called G-quadruplex (G4)." (PMID 35286386, 2022). "Overall, these findings highlight a novel role for Survivin in mediating the cooperative actions of KRAS and MYC during malignant transformation and raise the possibility that targeting Survivin may offer therapeutic benefits against KRAS-driven cancers." (PMID 36581205, 2022). "AMG510 demonstrated exquisite engagement selectivity for KRAS(G12C) compared with KRAS WT, other KRAS hotspot mutants, and HRAS WT, consistent with previous reports for functional selectivity between KRAS(G12C) and non-G12C driven cancer cell lines." (PMID 35314814, 2022). "KRAS, ARID1A, and PIK3CA are three genes, which are frequently muted in human cancers worldwide." (PMID 36072979, 2022). "The interaction between miRNAs and KRAS has been appraised in the context of cancer as well as non-malignant conditions." (PMID 35139853, 2022). "In KRAS-addicted lines, but not in normal cells or KRAS-independent cancer cells, this repression leads to the induction of apoptosis 16., 17., 18.." (PMID 35114566, 2022). "This comparative effectiveness research examines overall survival and cancer-specific survival in patients with or without KRAS sequence variation who received treatment for synchronous liver metastases." (PMID 36121654, 2022).
cancer (continued). "Notably, MUC1-C-induced ISGs in HPAF-II and AsPC-1 cells, as well as PDAC tissues, are similar with those identified in KRAS mutant, ductal-derived PDAC tumors and contribute to DNA damage resistance and cancer progression." (PMID 34657147, 2022). "Furthermore, these cancer pathways were jointly enriched in four genes, TCF7L2, NRAS, CTNNB1, and KRAS, which are mainly involved in cell proliferation." (PMID 36399471, 2022). "Considering the high prevalence of RAS point mutations in human tumors and the responsive role of BCL6 in KRAS oncogenic signaling, BCL6 inhibition may improve antitumor activity as a widely applicable approach in cancer therapy." (PMID 36377663, 2022). "However, it should be noted that KRAS activation is an early event in PDAC and maintained during cancer progression, thus ruling out that KRAS is the only determinant involved with the autophagy reliance observed in PDAC." (PMID 35159234, 2022). "In early-stage cancers, NNMT expression is higher in BRAF-mutated than in BRAF wild type tumors but is not affected by KRAS or PIK3CA mutation status." (PMID 35177765, 2022). "Previous reports have shown that KRAS inhibition triggers an improved immune response that drives T cell exhaustion, resulting in sensitivity to ICB in immunogenic models of KRASG12C-mutant cancer." (PMID 35857848, 2022). "In addition, these four cancer pathways were jointly enriched in four genes, CTNNB1, TCF7L2, NRAS, and KRAS, mainly involved in cell proliferation." (PMID 36399471, 2022). "Up to present, no effective pharmacological inhibitors for the KRAS oncoproteins has been approved for cancer treatment, leading to the perception that KRAS proteins are 'undruggable'." (PMID 35305671, 2022). "Besides, activating of oncogenic signaling pathways including PI3K-AKT-mTOR pathway, JAK-STAT pathway and KRAS-ERK pathway, can also induce PD-L1 expression in NSCLC or in other cancer types." (PMID 35346207, 2022). "KRAS influences the inflammatory milieu of cancer by activating the MAPK and PI3K signaling pathways, which results in the release of additional IL-6/IL-8 cytokines and cancer cell proliferation." (PMID 36776374, 2022). "Therefore, our work sheds light on a potential mechanism of resistance to KRAS inhibition: upon KRAS inhibition, cancer cells can continue to promote pro-tumorigenic properties on the fibroblasts, which in turn may support the survival of cancer cells through KRAS-independent mechanisms." (PMID 36010567, 2022). "First, the size range of the substances that enter KRAS mt cancer cells via macropinocytosis was not the maximum value of the theoretical volume of the macropinosome structures." (PMID 35154489, 2022). "Eight studies performed sequencing through different cancer‐related gene panels, and nine studies sequenced only predesignated genes including EGFR, KRAS proto‐oncogene (KRAS), B‐Raf proto‐oncogene (BRAF), erb‐b2 receptor tyrosine kinase 2 (ERBB2), and MET proto‐oncogene (MET)." (PMID 36000927, 2022).